RN7SL808P (RNA, 7SL, cytoplasmic 808, pseudogene)
Gene: Miscellaneous RNA gene on chromosome 4 (114,799,331 to 114,799,629, forward strand). Ensembl gene ENSG00000240637.
Homologues: Orthologues: chimpanzee Metazoa_SRP (97% identical), macaque Metazoa_SRP (83% identical). Paralogues in human: RN7SL3 (81% identical), RN7SL1 (80% identical), RN7SL2 (80% identical), RN7SL769P (78% identical), RN7SL230P (78% identical), RN7SL45P (78% identical), RN7SL607P (78% identical), RN7SL220P (78% identical), RN7SL300P (77% identical), RN7SL464P (77% identical), RN7SL551P (77% identical), RN7SL664P (77% identical), and 700 more.